CRP (C-reactive protein)
Diseases named in the same sentence as CRP in open-access papers (continued):
Sharing a sentence is not in itself a finding about the gene and the disease.
migraine (continued). "Furthermore, the severe headache or migraine group showed lower serum folate levels (11.6 vs 12.7, P < .001) compared to the control group, while also demonstrating higher levels of CRP (0.3 vs 0.2, P < .001) and BMI (27.9 vs 27.3, P < .001)." (PMID 39533580, 2024). "This study demonstrated that α-LA supplementation (300 mg/d, twice a day) for 3 months significantly decreased the serum levels of MDA and C-reactive protein (CRP), as two inflammatory and oxidative stress markers, and mood disorders in patients with episodic migraine." (PMID 39539367, 2024). "Three easy to measure blood markers (hs-CRP, HbA1c and phosphorus) could assist personalized metabolic migraine treatments and prophylactic interventions." (PMID 36882474, 2023). "However, several studies have reported that CRP levels between individuals with migraine and controls are unrelated." (PMID 36313504, 2022). "Further, high CRP levels have been reported in patients with migraine." (PMID 36313504, 2022). "Studies comparing C-reactive protein levels between adults with migraine and controls." (PMID 36313504, 2022). "Specifically, the levels of C-reactive protein (CRP) are elevated in serum of migraine patients." (PMID 30319363, 2018). "In migraine, specific abnormalities of inflammatory marker levels in the systemic circulation have been observed, including increased levels of C-reactive protein (CRP), interleukins, and adhesion molecules." (PMID 25595197, 2015). "However, conventional CRP assays may lack the sensitivity needed to detect low-grade inflammation, which could be present in migraine." (PMID 41402545, 2025). "Similarly, the C-reactive protein (CRP), a positive acute-phase protein that increases in response to inflammation, might play a role in migraine pathogenesis, but the findings are conflicting." (PMID 36982428, 2023). "However, the absence of correlation between hs-CRP level and WMHs suggests that hs-CRP is not causally involved in the pathogenesis of WMHs in migraine patients." (PMID 25595197, 2015). "The absence of an association between hs-CRP levels and WMHs may support the hypothesis that the hs-CRP level does not affect the brain pattern or severity of WMHs that are associated with migraine disease." (PMID 25595197, 2015). "C-reactive protein (CRP) is a biomarker of systemic inflammation and has been proposed as a candidate biomarker for migraine." (PMID 41402545, 2025). "A recent meta-analysis found significantly higher circulating levels of C-reactive protein (CRP), IL-1β, IL-6, and TNF-α in patients with migraine relative to healthy individuals." (PMID 41377228, 2025). "A meta-analysis revealed that serum levels of CRP, IL-1β, IL-6, and TNF-α were elevated in migraine patients compared to healthy controls." (PMID 40149800, 2025). "There are studies investigating the role of molecules such as C-reactive protein (CRP), fibrinogen, and prostaglandins (PGs) in the pathophysiology of neurogenic inflammation in migraines." (PMID 38535055, 2024). "C-reactive protein (CRP), a marker of inflammation and vascular disease, is elevated in individuals who suffer from migraine." (PMID 39519240, 2024). "included 10 studies with a total of 1842 participants, revealing significant elevations in serum CRP, IL-1β, IL-6, and TNF-ɑ levels among migraine patients, thus supporting the inflammation-related mechanisms proposed in this study." (PMID 39850553, 2024). "This study is, to the best of our knowledge, the first clinical trial evaluating the effects of inulin on migraine symptoms, mental health status, QOL, TOS, TAC, NO, zonulin, and Hs-CRP in women with migraines." (PMID 37951975, 2023). "Studies conducted on animal models have provided a possible link between IR and migraine, considering that several vascular mediators, interleukins or cytokines (TNF-α, C-reactive protein, IL-1β, IL-6, and IL-8), have an important role in both IR and migraine." (PMID 37886939, 2023).
migraine (continued). "Most recently, however, we showed that serum levels of proinflammatory biomarkers including CRP, TNF-α, interleukin-6, NO, and malondialdehyde positively correlated with number of migraine headache days per month." (PMID 34991456, 2022). "In contrast to these, CRP, a general inflammation marker, did not emerge as clearly useful in short-term prediction; changes in hs-CRP did not track well with migraine improvement in a 12-week trial, though CRP was elevated in migraineurs at baseline." (PMID 41377228, 2025). "In one study, C-reactive protein (CRP), a marker of inflammation, was found to be elevated in children with headaches, including migraines, compared to those without headaches." (PMID 41532064, 2025). "Previous studies assessing CRP or hs-CRP in migraine have not consistently accounted for headache status at the time of blood sampling." (PMID 41402545, 2025). "In MS patients with migraine, higher high-sensitivity C-reactive protein (hs-CRP) levels were detected compared to patients without migraine." (PMID 38674218, 2024). "Research has demonstrated that average plasma levels of C-reactive protein and homocysteine are higher in children who suffer from migraine compared to those who are not plagued by headaches." (PMID 37755358, 2023). "The other study presented that serum IL-6, CRP, and TNF-α were significantly higher in subjects who developed chronic migraines compared to episodic migraines and controls, and a positive correlation between headache frequency and serum IL-6 and TNF-α was confirmed." (PMID 37176049, 2023). "Compared with people without migraine, migraine sufferers are younger, more likely to be female, have a higher BMI, C-reactive protein, and lower uric acid and income-to-poverty ratio, and are less likely to engage in recreational activities." (PMID 37534030, 2023). "In contrast, studies on adult participants with a mean BMI of normal weight or less (< 25 kg/m2) showed no significant discrepancy in CRP levels between the migraine and control groups, except in a Turkish study." (PMID 36313504, 2022). "Multivariable linear regression analyses modified by age and BMI revealed that CRP did not significantly vary in compliance with clinical characteristics and comorbidities in the 365 participants with migraine." (PMID 36313504, 2022). "In conclusion, CRP levels are not statistically different between individuals with EM and individuals with CM and between individuals with migraine and healthy controls." (PMID 36313504, 2022). "Regarding migraine, a Brazilian study compared CRP levels between individuals with migraine and controls according to their BMI and found no significant discrepancy in CRP levels, both in the obese and normal-weight groups." (PMID 36313504, 2022). "A Chinese study assessed CRP levels after pine needle moxibustion in individuals with migraine but did not compare them to non-migraine controls." (PMID 36313504, 2022). "Several case-control studies and some population-based studies have found higher CRP values in migraine patients, but negative results have been reported by others." (PMID 31558164, 2019). "In agreement with the present results, a previous study have demonstrated that women with migraine had elevated CRP compared to women without migraine." (PMID 31558164, 2019). "CRP may be too nonspecific or slow changing to reflect migraine-specific inflammatory processes over short periods." (PMID 41377228, 2025). "However, as far as we are aware, no study thus far has compared CRP levels between individuals with migraine and controls in an Asian population." (PMID 36313504, 2022). "In 2018, we showed that serum levels of CRP and tumor necrosis factor alpha (TNF-α) did not correlate with frequency of migraine attacks." (PMID 34991456, 2022). "Similarly, differences in serum CRP and NLR levels between patients with frequent migraine attacks and those with infrequent attacks were not statistically significant (P&gt; 0.05)." (PMID 41799720, 2026).
migraine (continued). "Migraine sufferers (with and without aura) and obese patients have elevated plasma or serum concentrations of many inflammatory markers, including IL-1β, IL-6, IL-8, TNF-α, and C-reactive protein levels." (PMID 39600744, 2024). "In contrast, if an intervention improved headaches without affecting a cytokine (probiotics improving migraines without TNF change, or vitamin D/probiotic combo with no CRP change), it suggests that particular marker might not be a key driver of chronification in that context." (PMID 41377228, 2025).
Anorexia (72 papers, 2010 to 2026). Lack of desire to eat (loss of appetite). "C-reactive protein levels were higher in those with anorexia, vomiting, diarrhea, and weight loss compared to those without these symptoms." (PMID 36789985, 2023). "C-reactive protein was higher in those with symptoms of anorexia, vomiting, diarrhea, and weight loss compared to those without these symptoms." (PMID 36789985, 2023). "Serum concentrations of inflammatory biomarkers and cancer-related symptoms are related, and one study showed that interleukin-6 and C-reactive protein concentrations were associated with anorexia; however, interleukin-1ra was associated only with fatigue." (PMID 36407065, 2022). "Often as part of a pro-inflammatory state, anorexia is associated with raised levels of interleukin-6 (IL-6) and C-reactive protein (CRP) in people with cancer." (PMID 33510313, 2021). "The patients in the CC group had a significant weight loss over the previous 6 months, an increase in CRP levels, a decrease in serum hemoglobin concentration, and reported fatigue and/or anorexia." (PMID 31741709, 2019). "To illustrate, elevated level of C-reactive protein (CRP) was associated with pain, anorexia, dyspnoea, and fatigue in patients with cancer." (PMID 28542626, 2017). "After adjustment based on five factors, three factors were independently linked to global health status at T3: performance status, anorexia grade and CRP." (PMID 28449674, 2017). "A recent consensus definition has been proposed to include further factors to diagnose the cachexia syndrome such as involuntary weight loss, decreased muscle mass, anorexia, and biochemical alterations (C-Reactive Protein (CRP), albumin, haemoglobin)." (PMID 21760776, 2011). "Cachexia at discharge was defined by low body mass index combined with one or more of the following: low handgrip strength, elevated C-reactive protein, or anorexia." (PMID 41510342, 2025). "The results showed that Blautia was positively correlated with anorexia, HAMD scores, and CRP level, whereas Faecalibacterium, Bacteroides, Roseburia, and Parabacteroides were negatively correlated with anorexia, HAMD scores, and CRP level." (PMID 38698338, 2024). "This study suggested that MDD patients with anorexia had a distinct gut microbiota compared to healthy individuals, with higher level of CRP." (PMID 38698338, 2024). "Clinical symptoms such as fever, lassitude, fatigue, feelings of malaise, anorexia and increased levels of C-reactive protein (CRP) in inflammatory conditions are responsible for the high levels of plasma IL-6 and IL-1β." (PMID 33671159, 2021). "We used 28-day all-cause mortality as the dependent variable and anorexia, comorbidities, CD8+ count, lymphocyte count, CRP, D-dimer, LDH, high-sensitivity troponin I, osmotic pressure, PCT, and SOFA score on ICU admission as the independent variables." (PMID 33353956, 2020). "Systemically, IL-6 induces fever, fatigue, and anorexia as well as an increase in C-reactive protein (CRP)." (PMID 32655577, 2020). "Functional impairment, the presence of anorexia, the palliative nature of the chemotherapy and an elevated CRP dosage appear to be independent predictive factors of QoL in patients at the end of chemotherapy." (PMID 28449674, 2017). "The following data were collected: general health (performance status) and nutritional status (weight, anorexia grading, albuminemia, pre-albuminemia, and C-reactive protein) and QoL." (PMID 28449674, 2017). "A multivariate approach confirmed that the following parameters independently predicted QoL: performance status, anorexia, type of chemotherapy and CRP level." (PMID 28449674, 2017). "Functional impairment, the presence of anorexia, the palliative nature of the chemotherapy, and an elevated C-reactive protein dosage were independent predictive factors of a lower QoL among patients assessed at the end of chemotherapy." (PMID 28449674, 2017).
Anorexia (continued). "Besides the necessary criterion loss of weight, the most prevalent features in cachectic patients were increased CRP values and anorexia in more than three quarters of patients." (PMID 31029082, 2019). "Furthermore, reduced food intake, anorexia, markers of systemic inflammation like C-reactive protein (CRP), responsiveness to chemotherapy and the rate of cancer progression should be assessed for the diagnosis of cancer cachexia." (PMID 26856534, 2016). "The gut microbiota might have influenced MDD and anorexia through the inflammatory factor CRP." (PMID 38698338, 2024). "Blautia was more abundant in MDD patients with anorexia and positively correlated with CRP, HAMD scores, and anorexia." (PMID 38698338, 2024). "A correlation analysis showed that Blautia positively correlated with anorexia, HAMD scores, and CRP level, whereas Faecalibacterium, Bacteroides, Roseburia, and Parabacteroides negatively correlated with anorexia, HAMD scores, and CRP level." (PMID 38698338, 2024). "We found that the abundance of Blautia was positively correlated with anorexia, HAMD scores, and CRP level, whereas the abundance of Faecalibacterium, Bacteroides, Roseburia, and Parabacteroides were negatively correlated with anorexia, HAMD scores, and CRP level." (PMID 38698338, 2024). "Notably, we found that a higher abundance of Blautia in the MDA1 group was positively correlated with anorexia, the HAMD scores, and CRP level." (PMID 38698338, 2024). "In addition, inflammatory markers, such as IL1, IL6 and TNF-α which are known to induce anorexia or may have stronger impact on appetite and food intake compared with CRP, were not measured in the present study." (PMID 32618518, 2020). "Lipase activity, CRP, total MCAI, and UPASS were not significantly different when abdominal pain, lethargy, or anorexia were present or absent." (PMID 40452242, 2025).
pericarditis (72 papers, 2013 to 2026). An inflammatory process affecting the pericardium. "Pericarditis involves intense inflammatory activity, which causes elevation of different markers, such as C-reactive protein, erythrocyte sedimentation rate, neutrophils and platelets, serum amyloid A and D-Dimer." (PMID 39798014, 2025). "Newer diagnostic tools have been developed for this purpose, such as low-grade inflammation score (INFLA-score), a useful tool to assess the risk of pericarditis, with high diagnostic accuracy, even in patients with normal CRP." (PMID 39458001, 2024). "Diagnostic accuracy of blood RNA signatures and CRP for pooled analysis of Tb lymphadenitis and pericarditis." (PMID 38946942, 2024). "In a phase-3 RCT, rilonacept significantly reduced the risk of pericarditis recurrence, with patients showing rapid symptom resolution and normalization of CRP levels." (PMID 39458001, 2024). "The position and breathing-related pain were suggestive of pericarditis, associated with a mildly increased C-reactive protein (CRP), a discreet ST elevation, and a context of respiratory syncytial virus (RSV) infection." (PMID 38826682, 2024). "Normalization of CRP levels within one week has also been shown to identify patients with lower risk of recurrent pericarditis." (PMID 36498643, 2022). "The elevated CRP level was defined as one of the risk factors for unfavourable prognosis after acute pericarditis in adults." (PMID 31547038, 2019). "Compared with the diagnostic criteria in 2015, the 2025 diagnostic criteria for pericarditis consider clinical manifestations as a mandatory condition and elevate inflammatory markers, such as CRP, and cardiac magnetic resonance (CMR) findings to additional criteria." (PMID 41383610, 2025). "Laboratory findings for the whole cohort showed a significant increase in CRP, white blood cells and neutrophil values during the acute attack, which markedly reduced in the remission phase, underlining the role of the inflammatory burst in acute pericarditis." (PMID 39408004, 2024). "A study done with 200 cases of viral or idiopathic acute pericarditis showed that high-sensitivity CRP was an independent risk factor for the recurrence of pericarditis and should therefore be an additional consideration during initial therapy during a first episode of pericarditis." (PMID 40161164, 2025). "Pericarditis involves intense inflammatory activity and elevation of markers, such as CRP, erythrocyte sedimentation rate (ESR), white blood cells and their precursors, platelets, and other acute-phase reactants, which lack specificity and predictive value." (PMID 39798014, 2025). "Due to the extremely elevated CRP and abnormal CT, local doctors at the patient’s rural ER did not feel equipped to manage the patient since they believed her pericarditis was worsening." (PMID 40376326, 2025). "Most cases presented elevated inflammatory markers (ferritin and CRP) and/or concomitant pericarditis." (PMID 40336804, 2025). "Of note, among TB cases, the CRP levels in the pericarditis cohort were significantly higher than that of lymphadenitis cases." (PMID 38946942, 2024). "Start of anakinra 100 mg/day due to the persistence of sign and symptoms of pericarditis and new increase of PCR (C-reactive protein) values." (PMID 39469128, 2024). "This table compares key clinical variables such as WBC, CRP, maximal body temperature, and the incidence of pericarditis across several studies included in a systematic review." (PMID 39588448, 2024). "In our clinical case, the patient presented acute pericarditis with an inflammatory phenotype characterized by fever, chest pain, high levels of CRP and moderate pleuro-pericardial effusion." (PMID 39469128, 2024). "Recurrence of pericarditis was defined by the presence of two of the following: significant pericardial chest pain, CRP arising, and new or worsening pericardial effusion." (PMID 38399529, 2024).